MED21 (mediator complex subunit 21)
Description:
Component of the Mediator complex, a coactivator involved in the regulated transcription of nearly all RNA polymerase II-dependent genes. Mediator functions as a bridge to convey information from gene-specific regulatory proteins to the basal RNA polymerase II transcription machinery. Mediator is recruited to promoters by direct interactions with regulatory proteins and serves as a scaffold for the assembly of a functional preinitiation complex with RNA polymerase II and the general transcription factors.
Synonyms: hSrb7; SRB7; SURB7
Tractability: Small molecule: a structure with a bound ligand is known. PROTAC: ubiquitination databases record sites on it.
Gene: Protein-coding gene on chromosome 12 (27,022,546 to 27,066,343, forward strand). Ensembl gene ENSG00000152944.
Subcellular location: Nucleus
Subcellular location (Human Protein Atlas): Nucleoplasm; Cytosol; Nucleoli
Pathways (Reactome):
Developmental Biology: Transcriptional regulation of white adipocyte differentiation
Disease: RSV-host interactions
Metabolism: PPARA activates gene expression
Gene Ontology:
Molecular function: protein binding; transcription coactivator activity; DNA-directed RNA polymerase activity; transcription coregulator activity; ubiquitin protein ligase activity
Biological process: positive regulation of transcription by RNA polymerase II; positive regulation of transcription elongation by RNA polymerase II; positive regulation of transcription initiation by RNA polymerase II; regulation of transcription by RNA polymerase II; RNA polymerase II preinitiation complex assembly; protein ubiquitination
Cellular component: core mediator complex; mediator complex; nucleus; nucleoplasm; ubiquitin ligase complex
Genetic constraint (gnomAD): Loss-of-function variants: 5 observed, 12.04 expected, observed/expected ratio (o/e) 0.42, 90% interval 0.22 to 0.87. The upper end of that interval is the gene's LOEUF score, 0.87, which puts it in group 3 of 6, group 1 being the genes least tolerant of losing a copy. Missense variants: 123 observed, 146.11 expected, observed/expected ratio (o/e) 0.84, 90% interval 0.73 to 0.98. Synonymous variants: 61 observed, 51.62 expected, observed/expected ratio (o/e) 1.18, 90% interval 0.96 to 1.46.
Homologues: Orthologues: macaque MED21 (99% identical), pig MED21 (99% identical), rabbit MED21 (99% identical), rat Med21 (99% identical), mouse Med21 (98% identical), guinea pig MED21 (97% identical), chimpanzee MED21 (95% identical), dog MED21 (92% identical), zebrafish med21 (88% identical), tropical clawed frog med21 (86% identical), Drosophila melanogaster MED21 (55% identical), Caenorhabditis elegans mdt-21 (35% identical).
Diseases named in the same sentence as MED21 in open-access papers:
MED21 is named in the same sentence as 5 diseases in open-access papers, as found by Europe PMC text mining. Sharing a sentence is not in itself a finding about the gene and the disease. The quoted sentences say what the papers report.
metastatic melanoma (1 paper, 2021). A melanoma that has spread from its primary site to another anatomic site. "CYT-high metastatic melanomas had recurrent copy number amplifications in loci 1p12 (NOTCH2), 1q44 (OR2M4), 7q36.1 (KCNH2), 11q13.3 (FGF3/4), 12p11.23 (MED21) and 12q13.3 (R3HDM2) and deletions in 1p22.1 (RHOC, NRAS), 9p21.3 (CDKN2B), 10q23.2 (miR346), 11q23.3 (ATM, CHEK1, ETS1) and 15q15.3 (CASC4)." (PMID 33779796, 2021).
tumor (2 papers, 2015 to 2022). "In vivo, Med1, Med14, Med21, and Cdk8 have been shown to be required in hair follicle stem cells, plant meristem, mouse blastocysts, and tumor cells, respectively." (PMID 25772472, 2015). "The roles of MRPS35 and MED21 in tumor and immune regulation are still unknown, so further research is needed to explore the mechanism for the up-regulation of these genes and their implications for treatment." (PMID 36474268, 2022). "IFI27, LCN2, GAST, and SERPINA1 were downregulated after NACT in tumor cells, while OLFM4, MRPS35, MMP1 and MED21 were upregulated in tumor cells." (PMID 36474268, 2022).
MED21 also shares sentences with these, for which no sentence is quoted: café-au-lait macules (1 paper); cancer (1); lung adenocarcinoma (1).